CD44 (CD44 molecule (IN blood group))
Diseases named in the same sentence as CD44 in open-access papers (continued):
Sharing a sentence is not in itself a finding about the gene and the disease.
melanoma (continued). "HA/CD44 interactions with bone morphogenetic protein (BMP) promote BMP4/7-dependent Id1/3 protein expression in melanoma, contributing to reduced survival in melanoma patients." (PMID 35154001, 2021). "CD44 regulates the migration of fibroblast and can enhance as well abnormal epidermal function and melanoma development." (PMID 33440679, 2021). "In different models, ADAM10 and ADAM17 have been involved in the cleavage of CD44, mainly in melanoma cells." (PMID 33505471, 2021). "In supporting this, it was shown that ADAM10 and CD44 were found to be colocalized at the ruffling membrane structures in human melanoma cells." (PMID 34796172, 2021). "In other study, it was shown that cells expressing both CD133 and CD44 antigens create a vascular niche in melanoma xenografts." (PMID 33424978, 2020). "An MSC marker, CD105, as well as CD44, CD29, CD49e, and melanoma-associated chondroitin sulfate proteoglycan (MCSP) were found on the surface of ASC-exosomes." (PMID 32635660, 2020). "In agreement with our observations, WNT5a has been shown to increase Vimentin and CD44 to enhance motility of melanoma cells and nasopharyngeal carcinoma via the Ca2+ signaling pathway." (PMID 32546756, 2020). "Studies found that ADAM10 promoted cell migration via regulating modulation of CD44 in the pituitary adenoma cell and melanoma cell." (PMID 32256208, 2020). "The downregulation of RNF128 promotes the progression of melanoma by ubiquitination and degradation of CD44/cortactin to activate Wnt signaling, thereby inducing cellular EMT and obtaining stem cells." (PMID 33195233, 2020). "They demonstrated that doxorubicin delivered via this DDS reduced the tumor size up to 60%, compared to untreated control in a CD44+ mouse melanoma model." (PMID 32133350, 2020). "The attachment of hyaluronic acid on liposomes loaded with doxorubicin resulted in the selective binding of the DDS on CD44-expressing murine melanoma cells, resulting in a substantial reduction in the IC50." (PMID 32133350, 2020). "We found that the transcription factor SNAIL is up-regulated in melanoma tumors, whereas expression of CD44 and E-Cad is down-regulated." (PMID 32793477, 2020). "High levels of CD44 expression will be expressed in a poor diagnosis for melanoma patients when treated with decarbazine (DTIC)." (PMID 32117980, 2020). "The tumor suppressive miR-143-3p was identified as the most potent CD44 inhibitory miR, which affects growth characteristics of melanoma cells suggesting the implementation of miR-143-3p as as a potential anti-CD44 therapy of malignant melanoma." (PMID 31741714, 2019). "Consistently, cell-surface phenotype analysis indicated that the combinational treatment decreased CD44 expression on the surface of melanoma cells." (PMID 30717768, 2019). "CD44 correlates with HA staining in many cancers, such as squamous cell carcinoma and malignant melanoma." (PMID 30909497, 2019). "Overexpression of miR-143-3p in melanoma cells inhibits CD44 translation, which is accompanied by a reduced proliferation, migration and enhanced daunorubicin induced apoptosis of melanoma cells in vitro." (PMID 31741714, 2019). "IGF1R and CD44 are overexpressed in most advanced melanomas so we designed chemotherapeutic nanoparticles to target those receptors." (PMID 30824801, 2019). "Tris DBA-Pd nanoparticles are an effective therapy for CD44-positive tumors like melanoma, and further development of these nanoparticles should be pursued." (PMID 30824801, 2019). "According to the literature, melanoma TSCs are characterized by expression of antigens such as CD44, CD271, and CD133." (PMID 31234438, 2019). "In all cases analyzed the CD44 expression was stronger in melanoma cells when compared to the adjacent epidermal cells." (PMID 31741714, 2019). "Hyaluronic acid targets its receptor, CD44, which is expressed on melanoma stem cells and on aggressive tumor cells from multiple different types of tumors." (PMID 30824801, 2019).
melanoma (continued). "Some dominance of Rac signaling in CD44/CD44v-supported motility was also described in melanoma, where CD44v8-v10 promotes destruction of VE-cadherin junctions, which facilitates melanoma extravasation." (PMID 30211160, 2018). "Human melanoma cells transfected with an expression construct for the CD44 ectodomain showed retarded tumor growth." (PMID 29747682, 2018). "When considered in combination, these results demonstrate that endogenous CD44, similar to IL-13Rα2, plays a critical role in pulmonary melanoma metastasis and TGF-β1 production." (PMID 30165890, 2018). "The observation that melanoma cells expressing a truncated CD44 tail cannot migrate on HA, although retaining HA-binding capacity, supports this concept." (PMID 30211160, 2018). "Using FACS analysis, surface expression of CD44 was detected at high levels in both melanoma cell lines." (PMID 30297743, 2018). "CD133+ and CD44+ cells with their respective proliferative and invasive properties resemble the phenomenon of phenotype switching in melanoma tumors." (PMID 28241049, 2017). "For example, on primary melanoma cells expression of CD44 is higher than MCSP, which translated into a higher efficacy of the scFvFITC:sTRAIL when pretargeted with the anti-CD44 FITC-labelled antibody." (PMID 29038485, 2017). "In a transplant model of malignant melanoma, the ectodomain of CD44 significantly reduced the tumor volume because of inhibition of tumor cell proliferation." (PMID 29262593, 2017). "A screen of 51 purified monoclonal antibodies (mAbs) targeting cell surface-associated molecules revealed that two mAbs, anti-beta 1 integrin/(CD29) and anti-CD44, blocked melanoma cell coalescence." (PMID 28264026, 2017). "Our results demonstrate that macrophage-derived sLYVE-1 inhibits the proliferation of tumor cells by acting as a decoy receptor for LMW-HA, which induces proliferation in melanoma cells mainly via interactions with CD44." (PMID 29262593, 2017). "For example, the interaction of CD44 and its ligand, hyaluronic acid (HA), results in proliferation of eosinophils, B-cells, T-cells, keratinocytes, and human melanoma cells." (PMID 27220365, 2016). "Damm suggested that HGF stimulates the secretion of CD44 by melanoma cells by activating the nuclear factor-κB signaling pathway." (PMID 25658794, 2015). "In the B16 melanoma lung metastasis model, dendritic cells were pulsed with anti-CD44 coated apoptotic B16 melanoma cells." (PMID 25954275, 2015). "Reduction of CD44 molecules on the cell surface was also observed in human melanoma A2058 cell line after arazyme treatment." (PMID 24788523, 2014). "CD44 expression was seen in H2228, all the melanoma lines, with some increase in expression in SK-MEL-30 and COLO-800 in response to treatment." (PMID 25238228, 2014). "We followed the CD44 VE expression changes during tumour progression of two human melanomas, that express CD44 VEs at different orders of magnitude, in this experimental animal model." (PMID 23342032, 2013). "The intensity of CD44 staining was mostly weak in LN metastases, significantly reduced from the level in deep melanomas (p=0.020)." (PMID 23560496, 2013). "The moderate intensity of CD44 staining found in superficial and deep melanomas was thus decreased compared to strong staining in in situ melanomas (p=0.002 and p=0.000, respectively)." (PMID 23560496, 2013). "The adult primary tumour, newborn primary tumour and lung colony of HT199, the human melanoma cell line with low base CD44 VE expression level, all expressed the variable exons in the same order of magnitude and within the error bar." (PMID 23342032, 2013). "Immunostaining of the hyaluronan receptor CD44 showed relatively similar staining pattern as hyaluronan in different stages of melanoma." (PMID 23560496, 2013). "Our qualitative studies identified a melanoma-specific CD44 ASP, or fingerprint, which is different to the pattern of other examined tumour types." (PMID 23342032, 2013).
melanoma (continued). "In light of the complexity of CD44 isoform expression simple method to represent this pattern was developed which included v3 and v6– the exons considered to be of importance for melanoma progression." (PMID 23342032, 2013). "The role of CD44 in the progression of human melanoma has mostly been characterised by qualitative changes in expression of its individual variable exons." (PMID 23342032, 2013). "Expression of CD44 is decreased in melanomas inversely correlating with increasing size, depth and level of invasion, while uniform expression is found in benign nevomelanocytic lesions." (PMID 23560496, 2013). "We showed that all the variable exons are expressed in human melanomas and predicted a number of paralelly expressed CD44 isoforms." (PMID 23342032, 2013). "As the in vivo microenvironment is far more complex than the influences of the extracellular matrix, we used an animal model to evaluate the CD44 melanoma fingerprint in vivo." (PMID 23342032, 2013). "Similar to the coverage of CD44 staining, also the intensity of CD44 staining was further decreased in LN metastases compared to deep melanomas (p=0.007)." (PMID 23560496, 2013). "Elucidation of the role of CD44 and its alternative splice patterns in melanoma biology has been challenging." (PMID 23342032, 2013). "Ultimately, these results show that even in one of the ‘most simple’ CD44 fingerprints, melanoma, we cannot talk about ‘CD44’ as a single molecule anymore." (PMID 23342032, 2013). "The proportion of CD44-positive melanocytic cells was even lower (in 67% of samples coverage less than 76%) in LN metastases compared to deep melanomas (p=0.006)." (PMID 23560496, 2013). "ERK1/2 is a member of the central RAS pathway activated in nearly all melanomas, possibly linking hyaluronan and CD44 signaling with the activation of this pathway early in melanoma." (PMID 23560496, 2013). "Our analyses demonstrated, that although the melanoma CD44 fingerprint is qualitatively stable, quantitative changes are observed suggesting a possible role in tumour progression." (PMID 23342032, 2013). "In our previous studies, we have shown that melanoma cells and ECs can show differential susceptibility to LAK lysis based on the expression of CD44 variant isoforms." (PMID 22532866, 2012). "Although the B16F10 cell line is of murine origin, it highly expresses CD44 and serves as a good in vivo model of aggressive human melanoma." (PMID 23213537, 2012). "The IC50 value for our CD44-targeted liposome is slightly higher (approximately 9-10 μM), but we have examined activity against a highly aggressive human melanoma cell line." (PMID 23213537, 2012). "BJ fibroblasts have ~60% of the CD44 content of M14#5 melanoma cells, while M14#11 melanoma cells have ~75% of the CD44 content." (PMID 23213537, 2012). "In melanoma, CD24 is part of the CD44+CD133+CD24+ stem cell-like immunophenotype in B16-F10 mouse melanoma cells and is upregulated in these cells during in vivo tumor formation." (PMID 23166783, 2012). "In the CD44+ B16F10 mouse melanoma model, CD44-targeted liposomes reduced the tumor size to 60% of that of the untreated control, whereas nontargeted liposomes were ineffective." (PMID 23213537, 2012). "S100A1, S100B, Bcl-2, and CD44 have been described in transformation of melanocytes to melanoma cells." (PMID 20936153, 2010). "CD44/HCAM is also a cell adhesion protein interacting with matrix components, and expression in melanoma cells has been linked to poor prognosis in some but not all studies." (PMID 19061491, 2008). "Expression of the αv and β3 integrin subunits and of osteopontin was stronger in melanomas than in benign nevi (p = 0.034, p = 0.001 and p < 0.0001, respectively), whereas the expression of CD44 was weaker in melanomas than in nevi (p = 0.038)." (PMID 19061491, 2008). "We have reported previously that OPN expression in human melanoma cells increases CD44 surface expression, MMP-2 secretion, and cell migration." (PMID 17343740, 2007).
melanoma (continued). "We have previously shown the interaction of MMP-2 with cell surface CD44 in human melanoma cells over expressing OPN." (PMID 17343740, 2007). "For instance, CD44 and ICAM1 are key adhesion molecules implicated in tumor cell migration, metastasis, and modulation of the immune response, with ICAM1 upregulation on melanoma cells and exosomes linked to enhanced metastatic potential and immune escape." (PMID 40805206, 2025). "For example, while CD44 is an abundant protein in all cells, including melanocytes, it was puzzlingly undetectable in normal melanocyte exosomes for all four donors, yet present in malignant melanoma-derived exosomes." (PMID 40805206, 2025). "Furthermore, it has been demonstrated that melanoma progression primarily occurs in a CD44-regulated manner." (PMID 41465475, 2025). "Hyaluronic acid (HA) activation of CD44 enhances the migration of melanoma and other tumor cells." (PMID 40046628, 2025). "CD44 is a cell surface glycoprotein that has been identified as a CSC marker in melanoma." (PMID 39518076, 2024). "Additionally, the activation of the Wnt signaling pathway in melanoma is known to occur through the ubiquitination and degradation of CD44 and cortactin by RNF128, subsequently inducing EMT and stemness in melanoma cells." (PMID 38886806, 2024). "Bead-based multiplex analysis revealed the robust expression of the sEV tetraspanins CD9, CD63, and CD81 in addition to CD29 (Integrin beta- 1), the MSC-EV-specific markers CD44 (hyaluronic acid receptor) and MSCP/NG2 (melanoma‐ associated chondroitin sulfate proteoglycan)." (PMID 38764077, 2024). "However, high-CD44-expression patients exhibited an extended PFS compared with low-CD44-expression patients in Gide2019_PD1+CTLA4-Melanoma and Prat2017_PD1-NSCLC-HNSC-Melanoma cohorts." (PMID 38590654, 2024). "Further, we verified the value of CD44 as a predictor for ICB efficacy, as a result, CD44 down-regulation was related to better immunotherapy response in a melanoma cohort undergoing anti-PD-1 therapy (GSE91061), and CD44 expression of non-response group markedly elevated." (PMID 38590654, 2024). "Additionally, by using a CD44 antibody to partially inhibit extracellular FN signaling, a significantly decrease in adhesion and survival of melanoma cells was obversed." (PMID 38783892, 2024). "CD44 has been shown to be a major mediator of hyaluronic-acid-mediated melanoma cell proliferation, and its high levels correlate with disease progression and poor survival in melanoma patients." (PMID 39594665, 2024). "In contrast, commercial PTX product and non-targeted variant, i.e., PTX@BSA NPs endowed 19.04 ± 4.12 μg/ml and 28.34 ± 5.28 μg/ml, respectively, suggesting CD44 targeted chemotherapy is an efficient strategy to treat melanoma with low-cost HA as a targeting moiety." (PMID 36635761, 2023). "It was shown that ADAM10 or ADAM17-mediated cleavage of CD44 is triggered upon different stimulation e.g., by Ca2+ influx or protein kinase C (PKC) activation, whereas a study on melanoma cells indicated that constitutive and endogenous shedding of CD44 is mediated by ADAM10." (PMID 36876041, 2023). "Indeed, TRM cells (CD8+/CD103+/CD69+/CD44+) in normal skin lack immune checkpoints and are critical for protection against melanoma by eliminating major histocompatibility complex (MHC) class I positive melanoma cells." (PMID 37334356, 2023). "Such a rational design presents a preferential accumulation tendency to tumor sites due to the active CD44‐targeting mechanisms, specifically achieves remarkable systematic energy exhaustion in melanoma cells, and affords 80.8% in tumor growth suppression without systemic toxicity in vivo." (PMID 34913610, 2022). "Our findings propose that targeting of NRF2 in melanoma could lead to CD44 up‐regulation, which enhances survival of melanoma cells." (PMID 34951143, 2022).
melanoma (continued). "Interestingly, a recent study investigating changes in the melanoma proteome following NRF2 modulation revealed that the inhibition of NRF2 expression led to changes in the expression of genes related to melanoma progression including stem cell marker CD44." (PMID 35326683, 2022). "Additionally, with the aid of specific binding between HA and CD44, which is highly expressed on the surface of melanoma cells (B16F10), the drug can be targeted for delivery to melanoma, thereby attenuating toxicity and enhancing anti-tumor activity." (PMID 34452196, 2021). "In addition, CD44 is highly expressed on the surface of various malignant tumor cells, including melanoma, and ovarian and breast cancers." (PMID 34452196, 2021). "Collagen type IV was shown to promote adhesion, migration, and spreading of melanoma cells via interaction with chondroitin sulfate proteoglycan via CD44 or β1 integrin involving the signaling cascades related to p(Tyr127)FAK and paxillin, PI3-kinase, and protein kinase C (PKC)." (PMID 34440617, 2021). "In melanoma, the expression of CD44 decreases gradually with increasing invasiveness." (PMID 33854593, 2021). "Recombinant analog of mambalgin-2 cancelled acidification-induced proliferation, migration, and invasion of metastatic melanoma cells, promoted apoptosis, and down-regulated cell-surface expression of prooncogenic factors CD44 and Frizzled 4 and phosphorylation of transcription factor SNAI." (PMID 34680442, 2021). "rVAR2 pulled down glycosylated CD44 from melanoma protein lysates." (PMID 32938749, 2021). "Moreover, anti-CD44 mAbs have been shown to affect cancer cell motility and aggregation of breast tumor and melanoma cell lines in a 3D Matrigel model, in the apparent absence of hyaluronic acid (HA)." (PMID 33891595, 2021). "The interaction of rVAR2 with the CS-modified form of CD44 in melanoma cells was validated." (PMID 32938749, 2021). "We propose that the down-regulation of CD44 expression may also inhibit its possible interaction with NHE1 in melanoma cells that may lead to dysregulation of intracellular pH balance." (PMID 34680442, 2021). "Specifically, CD44-binding peptide A5G27 showed significant inhibitory effect on tumor growth and metastasis in a mouse melanoma model, while another CD44-targeting peptide, A6, inhibited migration, invasion, and metastatic potential of prostate, breast and ovarian cancer cells." (PMID 33335857, 2020). "AFM force spectroscopy was used to map CD44-coupled surface receptors of melanoma cells." (PMID 32117980, 2020). "In the context of tumor vascularization, epithelial cells from the blood vessels of solid tumors show increased CD44 levels compared with normal tissue samples, and CD44 inhibition blocks tumor induced angiogenesis in human melanoma and laryngeal cancer models." (PMID 33335857, 2020). "Therefore, this study aimed to identify the most potent CD44-regulatore miRs published so far in melanoma with the highest potential for miR-143-3p." (PMID 31741714, 2019). "Furthermore, patients with high CD44 expression levels in malignant melanoma have a statistical significantly decreased 5 years’ OS in comparison to the CD44 low group." (PMID 31741714, 2019). "The multistructural and multifunctional transmembrane glycoprotein CD44 is overexpressed in many tumors of distinct origin including malignant melanoma and contributes to a poor prognosis by affecting cell proliferation, cell migration, and also the sensitivity for apoptosis induction." (PMID 31741714, 2019). "There, the role of known CD44-regulatory miRs was analyzed in melanoma." (PMID 31741714, 2019). "Indeed, in vitro melanoma models showed that tumor cells overexpressed CD44 under acidic conditions (through lactate response elements in CD44-promoter) to retain hyaluronic acid on their surface and to favor their aggressive phenotype." (PMID 30708988, 2019).